STAG1 (STAG1 cohesin complex component)
Diseases named in the same sentence as STAG1 in open-access papers (continued):
Sharing a sentence is not in itself a finding about the gene and the disease.
cancer (39 papers, 2017 to 2026). A tumor composed of atypical neoplastic, often pleomorphic cells that invade other tissues. "Although STAG2 genetic changes are more commonly linked to cancer, some STAG1 variants have been implicated in tumorigenesis by affecting chromatin architecture and leading to oncogenic gene misregulation." (PMID 40361893, 2025). "STAG1 represents the vulnerability of cancer cells that carry mutations in the major emerging tumor suppressor STAG2 in different cancer environments." (PMID 39390002, 2024). "Using synthetic lethal interactions to target recurrent cohesive protein mutations in cancer, for example by inhibiting STAG1, holds promise for the diffusing of selective treatments." (PMID 39390002, 2024). "STAG2 is a frequent target of inactivating mutations in human cancers, which are only partially compensated for by its paralogue, STAG1." (PMID 35287703, 2022). "Based on our screen results and those of others, it seems unlikely that a “loss-of-function” therapeutic target beyond STAG1 will be discovered that will work in all diverse cancer types with STAG2 loss." (PMID 34462321, 2021). "STAG1 inhibition in cancer cells with STAG2 mutation causes chromosome segregation defects and subsequent lethality." (PMID 33284104, 2020). "STAG1 represents a vulnerability of cancer cells carrying mutations in the major emerging tumor suppressor STAG2 across different cancer contexts." (PMID 28691904, 2017). "Exploiting synthetic lethal interactions to target recurrent cohesin mutations in cancer, e.g. by inhibiting STAG1, holds the promise for the development of selective therapeutics." (PMID 28691904, 2017). "Hence, targeting STAG1 in STAG2-mutated cancer cells is an attractive therapeutic approach." (PMID 38033389, 2023). "Several studies have proved that STAG1 inactivation imparts a potent synthetic lethality in STAG2-mutant cancer cells 49-51." (PMID 35371307, 2022). "The core complex subunits SMC1A, SMC3, STAG1/2, and RAD21 as well as its modulators, have been found to be recurrently mutated in human cancers." (PMID 35287703, 2022). "Similar strategies are currently being explored for STAG1 and STAG2, two paralogs of cohesin subunits, and shows the depletion of STAG1 selectively kills SATG2-deficient cancer cells." (PMID 34070827, 2021). "Blocking this interaction was highlighted as another potential avenue for therapeutic targeting of STAG1 in STAG2 mutant cancers." (PMID 34202641, 2021). "STAG1: Synthetic lethal interaction between STAG1/2 paralogs has been identified in several cancer cells." (PMID 34202641, 2021). "Although these results implicate STAG1 as a promising target for selective eradication of STAG2-mutant cancer cells, STAG1 has been shown to be essential for embryonic development, potentially because of gene regulatory functions that remain poorly understood." (PMID 32467316, 2020). "Thus, STAG1-directed small molecule degraders that engage a suitable human E3 ligase such as VHL or CRBN may provide a promising therapeutic modality for the treatment of STAG2-mutated cancers." (PMID 32467316, 2020). "The cancer-specific pattern is exemplified in the STAG1 locus, in which three of four genes within the 800 kb window are significantly correlated with AC096992.2 in AML." (PMID 30767760, 2019). "We provide strong evidence that STAG1 is a promising therapeutic target in cancers with inactivating alterations of STAG2." (PMID 28430577, 2017). "We inhibited STAG1 and STAG2 in several cancer cell lines where the two genes have variable mutation and copy number status." (PMID 28430577, 2017). "To prove that the synthetic lethality between STAG1 and STAG2 is context independent, we have tested their genetic interaction in several cancer cell lines where the two genes have variable mutational and copy number status." (PMID 28430577, 2017).
cancer (continued). "Our data on SK-ES-1 cells, which have inactive STAG2 gene, show that this vulnerability can be exploited to specifically target STAG2-altered cancers by developing specific STAG1 inhibitors." (PMID 28430577, 2017). "Among these genes, AURKA and STAG1 play important roles in cell division by regulating chromosome segregation and mitotic spindle formation and are considered promising targets for cancer therapy." (PMID 40815637, 2025). "STAG1 (5%), NIPBL (4.9%), STAG2 (3.4%) and PDS5B (3.4%) are the most frequently mutated in cancer." (PMID 35287703, 2022). "Furthermore, after mapping the non-synonymous mutations onto the internal branches of the CellPhy tree, we found that all cancer cells harbor somatic variants affecting genes that can contribute to human intestinal neoplasia (i.e., MYH11 and STAG1)." (PMID 35081992, 2022). "To determine whether the dependence of STAG2-mutated cells on STAG1 was a generalizable interaction beyond our three paired backgrounds, we examined the AVANA CRISPR Cancer Dependency Map (DepMap) dataset." (PMID 34462321, 2021). "In cancer, the STAG2 gene is more highly mutated than any other cohesin component, including STAG1." (PMID 34462321, 2021). "While cancer-associated mutations in genes encoding RAD21, SMC3, and STAG1 are always heterozygous, mutations in the X chromosome-located genes SMC1A and STAG2 can result in complete loss of function due to hemizygosity (males), or silencing of the wild type during X-inactivation (females)." (PMID 33284104, 2020). "Both STAG1 and STAG2 acquire somatic LoF alterations (homozygous gene deletions, truncating mutations and multiple hits) as well as putative damaging missense and splicing mutations in a variety of human cancers of The Cancer Genome Atlas (TCGA)." (PMID 28430577, 2017). "However, mutations in STAG2, but not STAG1, occur frequently in various cancers, suggesting a unique role of STAG2 in cancer biology." (PMID 35388001, 2022). "Notably, the ratio of Stag2 transcripts to Stag1 transcripts in wild-type mESCs is 1.08, which is lower than most of the ~ 1000 cell lines in the Cancer Cell Line Encyclopedia, indicating that other cell types operate with a relatively higher level of cohesin-STAG2 than cohesin-STAG1." (PMID 32778134, 2020). "Finally, we asked whether the reported synthetic lethality observed upon depletion of STAG1 in STAG2-null cancer cells also occurred in mESCs." (PMID 32778134, 2020). "Furthermore, expression analysis did not reveal upregulation of STAG1 protein or mRNA as a major compensatory mechanism for the loss of STAG2 function in cancer cell lines or patient tumors." (PMID 28691904, 2017). "In support of this model, elevated expression of almost every cohesin subunit (RAD21, SMC1A, SMC3, STAG1, PDS5, WAPL) and cohesin regulator (NIPBL, MAU2) appears to be oncogenic and present in a wide range of cancer cells." (PMID 41370327, 2025). "Our results move beyond protein-coding gene regulation via chromatin loops to new roles for STAG1 in nucleolar structure and function, and offer fresh perspectives on how STAG proteins, known to be cancer targets, contribute to cell identity and disease." (PMID 37802073, 2023). "Cancer cells depend on the overlapping function of STAG1 in STAG2 knockout cell lines to maintain the integrity of chromatin cohesion; double knockout of STAG1 and STAG2 induces synthetic lethality." (PMID 37444402, 2023). "Cancer growth can also be reliant on high expression of specific E2 cell cycle target genes including AURKA, KIF4A, STAG1, CTCF, and RPA1, all of which were identified highly expressed in at least one of the at-risk samples studied here." (PMID 35459280, 2022). "To validate the predicted synthetic lethal interaction between STAG1 and STAG2, we inactivated them in the CAL-51 cancer cell line where both genes are WT." (PMID 28430577, 2017).
cancer (continued). "This condition mimics that of cancer samples where STAG2 is somatically inactivated and supports the development of STAG1 as a therapeutic target in these tumours." (PMID 28430577, 2017). "Although paralogous synthetic lethal pairs like STAG1/STAG2 and IREB2/ACO1 are interesting biologically, how the large therapeutic window of these paralogous synthetic lethal interactions can be translated into potential cancer therapeutics is an open question." (PMID 34462321, 2021). "Our findings not only establish a previously unknown role of the STAG2 to STAG1 switch in 3D genome organization, but also reveal a functional link between STAG2 and interferon signaling in cancer cells, which may enhance the immune evasion potential in STAG2-mutant cancer." (PMID 35388001, 2022). "STAG1 inactivation has little if any impact on the viability and proliferation of STAG2 wild-type cancer cells and non-transformed cells, but is essential for survival in the absence of STAG2." (PMID 28691904, 2017).
tumor (24 papers, 2013 to 2026). "In contrast to tumors expressing a neutral control shRNA, two independent shRNAs targeting STAG1 strongly suppressed tumor growth in vivo." (PMID 32467316, 2020). "Using a variety of experimental approaches and cell lines, we show that STAG1 and STAG2 are synthetic lethal partners and provide evidence that STAG1 is a potential therapeutic target in tumours where STAG2 is inactive." (PMID 28430577, 2017). "To support our hypothesis, we also investigated the transcriptional activity of STAG1 and the tumor angiogenesis promoting factor, VEGFA." (PMID 36052535, 2022). "Taken together, these studies showed that downregulated PDGFRA may be negatively regulated by STAG1 TF in HCC cells but positively correlated with the emerging vessels surrounding the tumor lesion." (PMID 36052535, 2022). "Up-regulation of ten DEGs in PAAD tumor is in concordance with the up-regulation of master regulators CTCF, IRF1, and KLF4, while POLR2A and STAG1 remain unchanged." (PMID 35453789, 2022). "Two SNVs are also present in genes (STAG1 (F802Y) and NUMA1 (L1400P)) in this pathway and suggest the importance of these alterations in this tumor." (PMID 24204627, 2013). "Here we identify STAG1 as a strong genetic vulnerability of cells lacking the major emerging tumor suppressor STAG2." (PMID 28691904, 2017). "In the tumor state, these disease-related genes can regulate some famous oncogenes, like SETD2 and STAG1, but not in the normal state." (PMID 34335688, 2021).
neurodevelopmental disorder (8 papers, 2021 to 2025). A behavioral and cognitive disorder with onset during the developmental period that involves impaired or aberrant development of intellectual, motor, or social functions. "STAG1 pathogenic variants are associated with a spectrum of neurodevelopmental disorders, collectively named cohesinopathies." (PMID 40361893, 2025). "Here, we report, for the first time, two monozygotic twins affected by a syndromic neurodevelopmental disorder associated with a de novo variant in the STAG1 gene." (PMID 39336775, 2024). "We herein describe for the first time a pair of twins affected by a neurodevelopmental disorder associated with a de novo variant in the STAG1 gene." (PMID 39336775, 2024). "Methods and Results: We report, for the first time, two twins affected by a syndromic neurodevelopmental disorder associated with a de novo variant in the STAG1 gene." (PMID 39336775, 2024). "Pathogenic variants in STAG1 gene have recently been reported to cause an emerging syndromic form of neurodevelopmental disorder that is to date poorly characterized." (PMID 34440290, 2021).
hematological malignancies (3 papers, 2022 to 2024). "In consideration of the recently reported possible role of STAG1 alterations in predisposition to childhood hematological malignancies, we programmed a tailored hematological follow-up for our probands." (PMID 39336775, 2024). "This aspect implies that patients with STAG1 pathogenic variants could benefit from long-term monitoring to promptly detect hematological malignancies." (PMID 39336775, 2024). "The downregulation of STAG1 in PAD may be associated with genomic stability or predispose tissues to DNA damage since mutations in STAG1 have been reported to predispose children to hematological malignancies." (PMID 39120300, 2024).
psychiatric disorder (1 paper, 2025). A disorder characterized by behavioral and/or psychological abnormalities, often accompanied by physical symptoms.
STAG1 also shares sentences with these, for which no sentence is quoted: infection (12 papers); mastitis (5); colon carcinoma (3); diabetes (2); lysosomal storage disorders (2); Neurodevelopmental delay (2); bipolar disorder (1); central precocious puberty (1); chronic myelogenous leukemia (1); Cognitive impairment (1); cystic fibrosis (1); depression (1); epileptic encephalopathies (1); Fabry disease (1); gastric cancer (1); genetic disorders (1); gynecologic cancer (1); Hodgkins lymphoma (1); hydatidiform mole (1); hyperamylasemia (1); Hypertension (1); lung carcinoma (1); medulloblastoma (1); microcephaly (1); Micrognathia (1); myelodysplastic syndrome (1); myocardial infarction (1); osteosarcoma (1); parathyroid tumors (1); Pectus excavatum (1).
A further 10 diseases each share a sentence with STAG1 in 1 paper.